FOLR1 (folate receptor alpha)
Diseases named in the same sentence as FOLR1 in open-access papers (continued):
Sharing a sentence is not in itself a finding about the gene and the disease.
melanoma (4 papers, 2018 to 2023). A malignant, usually aggressive tumor composed of atypical, neoplastic melanocytes. "In contrast, a control MOv18 IgE antibody, targeted toward a different antigen, folate receptor-alpha, which is not expressed by A375 melanoma cells, and used here as a nonspecific isotype control, showed much lower T/B and T/M ratios than those of the anti-CSPG4 antibodies at 24–120 h." (PMID 34513315, 2021).
metastatic disease (4 papers, 2016 to 2025). "In both localized and metastatic disease models, human T cells were detected in peripheral blood on day 5, with increased population detected in mice treated with FH FOLR1-CART compared with a negligible population in mice that received NT T cells." (PMID 40919994, 2025). "Although the standard U-2 OS cell line was used as a pilot study to establish both localized and metastatic disease models in mice, the patient-derived tumor cell line OS9 was used to evaluate in vivo FH FOLR1-CART activity in a metastatic model." (PMID 40919994, 2025).
pancreatic ductal adenocarcinoma (4 papers, 2017 to 2025). An infiltrating adenocarcinoma that arises from the epithelial cells of the pancreas. "In pancreatic ductal adenocarcinoma (PDAC), folate receptor alpha (FRα) and death receptor 4 (DR4) are significantly overexpressed and are typically associated with a poor prognosis." (PMID 40705122, 2025).
renal cell carcinoma (4 papers, 2011 to 2023). "SFRP1 and FOLR1 have a greater association with urologic tumors, like renal cell carcinoma or kidney cancer." (PMID 35719392, 2022).
glioma (3 papers, 2019 to 2024). A benign or malignant brain and spinal cord tumor that arises from glial cells (astrocytes, oligodendrocytes, ependymal cells). "On the contrary, CNV gain for FOLR1 was detected in 57.14% of low-grade gliomas, with 28.57% of CNV loss (data obtained from seven cases)." (PMID 31003476, 2019). "We conclude that the PCFT provides a mechanism for targeted delivery of drugs to some gliomas as a starting point for the development of efficient methods for treating gliomas with high expression of PCFT and/or FOLR1." (PMID 31003476, 2019). "Tissue samples were homogenized using collagenase/hyaluronidase and glioma cells were purified from the specimens with use of Percoll gradients, in order to remove blood and endothelium cells that might express PCFT and/or FOLR1." (PMID 31003476, 2019). "No significant expression of folate receptor 1 (FOLR1) was detected in glioma cells." (PMID 31003476, 2019).
leukemia (3 papers, 2021 to 2023). A malignant (clonal) hematologic disorder, involving hematopoietic stem cells and characterized by the presence of primitive or atypical myeloid or lymphoid cells in the bone marrow and the blood. "After 1 week, unmodified or FOLR1 CAR T cells were injected into the leukemia-bearing mice at 1 × 107 cells (1:1 CD4+/CD8+ cell ratio) per mouse." (PMID 36136600, 2022). "We note that in the WSU-AML–bearing mice that relapsed following CAR T treatment, the leukemia cells did express FOLR1." (PMID 36136600, 2022). "In C/G-CB (>9 weeks in EC coculture), WSU-AML, and Kasumi-1 FOLR1+ xenograft models, treatment with FOLR1 CAR T cells resulted in leukemia clearance, while disease progression occurred in all mice that received unmodified T cells." (PMID 36136600, 2022). "We confirmed FOLR1 expression by the AML cells that engrafted in the unmodified T cell–treated mice and in one of the CAR T–treated mice that developed symptomatic leukemia on day 180 after T cell injection." (PMID 36136600, 2022). "Importantly, treatment with FOLR1 CAR T cells significantly extended the median survival in mice bearing C/G-CB, WSU-AML, and Kasumi-1 FOLR1+ leukemias." (PMID 36136600, 2022). "We have identified FOLR1 as a unique and specific target expressed in C/G AMKL and developed a potent CAR T cell that effectively eliminates C/G leukemia cells while sparing normal HPSCs, providing a potential therapeutic approach for this high-risk AML subtype." (PMID 36136600, 2022). "The evidence that FOLR1 is causally linked to the C/G fusion and uniquely expressed in AML blasts suggested that targeting FOLR1 may provide a specific strategy to eliminate C/G leukemia without impacting normal hematopoiesis." (PMID 36136600, 2022). "The activity of FOLR1 CAR T cells in vivo was target specific, as they did not limit the leukemia progression nor extend the survival of Kasumi-1 xenografts." (PMID 36136600, 2022).
medulloblastoma (3 papers, 2017 to 2023). A malignant, invasive embryonal neoplasm arising from the cerebellum. "Currently we detected the expression of Folr1 in medulloblastoma and identified the diagnostic application by evaluating the clinical, pathological and neuroimaging values." (PMID 28416738, 2017). "Folr1 expression was up-regulated in medulloblastoma and positively correlated with percentage of Ki-67 and MMP9 labeling, pathological subtypes, serum Folr1 levels and CSF spreading on MRI." (PMID 28416738, 2017). "Strong Folr1 expression was recommended as the independent value regarding the prognosis of patients with medulloblastoma." (PMID 28416738, 2017). "Then we developed a target therapeutic compound with Folr1, which exhibited promising efficiency in treatment of medulloblastoma." (PMID 28416738, 2017). "Our findings uncovered in Folr1 a predictive candidate and therapeutic target for medulloblastoma." (PMID 28416738, 2017).
Obesity (3 papers, 2014 to 2024). Accumulation of substantial excess body fat. "The weak inverse association in univariable analyses between obesity assessed by BMI and serum FOLR1 concentrations indirectly supports the in vitro observations that the FOLR1 gene promoter is repressed in the presence of 17β-estradiol." (PMID 24810481, 2014). "This suggests appropriate adaptation in folate transfer across the placenta, that has been suggested to include a downregulation of FOLR1 gene expression in the placenta with obesity." (PMID 30428605, 2018). "Placental mRNA abundance for the folate receptor alpha (FOLR1) was reduced with obesity, whilst DNMT1 was increased with raised BMI, responses that were unaffected by GD." (PMID 30428605, 2018). "Raised mRNA abundance of FOLR1, if translated to protein, and accompanied with a decline in maternal folate concentration would result in the maintenance of cord blood folate as we observed at term with obesity." (PMID 30428605, 2018). "For example, adipose tissue can produce 17β-estradiol, and the increasing prevalence of obesity may influence in vivo FOLR1 expression." (PMID 24810481, 2014).
Alzheimer disease (2 papers, 2022 to 2024). A progressive, neurodegenerative disease characterized by loss of function and death of nerve cells in several areas of the brain leading to loss of cognitive function such as memory and language. "Moderate Alzheimer’s disease (Braak III-IV) and MS CSF had significantly reduced folate and FOLR1 but normal FDH, indicating a possible failure in folate transport from the blood into the CSF but no loss of FDH from the brain." (PMID 39337690, 2024). "Folate can also enter with FOLR1 into GFAP-positive astrocytes, and this process becomes important in abnormal conditions such as Alzheimer’s disease." (PMID 39337690, 2024).
autoimmune disease (2 papers, 2022 to 2025). A disorder resulting from loss of function or tissue destruction of an organ or multiple organs, arising from humoral or cellular immune responses of the individual to their own tissue constituents. "Autoantibodies toward folate receptor alpha (FRα) were also found in ASD children, autoantibodies that are involved in autoimmune diseases development and oxidative stress." (PMID 36339838, 2022).
benign ovarian tumor (2 papers, 2018 to 2019). "In this study, we found that FOLR1 was upregulated in OC tissues compared with the normal ovarian tissues and benign ovarian tumor as well." (PMID 31049278, 2019). "The expression of FOLR1, DHFR, and MTRR was evaluated in 80 cases of primary OC, 50 cases of benign ovarian tumors, and 30 normal ovarian tissues." (PMID 31049278, 2019).
bladder cancer (2 papers, 2020 to 2021). "Taken together, TPP1, TMPRSS2 and FOLR1 could all be possible prognostic markers and treatment targets in bladder cancer." (PMID 32249794, 2020). "Currently, two CAR-T cell approaches targeting the folate receptor alpha (FRα) and the prostate-specific membrane antigen (PSMA) are in phase I/II studies for bladder cancer (NCT03185468)." (PMID 34123841, 2021).
Cerebral (2 papers, 2024 to 2025). "Cerebral folate transporter deficiency (CFD) is a disease with autosomal recessive transmission due to mutations in folate receptor 1 gene (FOLR1) (OMIM#613068), which encodes folate receptor alpha (FRα)." (PMID 40218241, 2025). "FOLR1-related cerebral folate transport deficiency (FOLR1-CFTD) presents in the second and third years of life." (PMID 39328591, 2024).
chronic periodontitis (2 papers, 2019 to 2020). A chronic inflammatory process that affects the tissues that surround and support the teeth. "The corresponding mean ± SD GCF FOLR1 levels were: 15.16 ± 7.25 pg/ml in healthy group, 37.3 ± 11.1 pg/ml in gingivitis group and 37.92 ± 12.9 pg/ml in chronic periodontitis group." (PMID 31604439, 2019). "GCF FOLR1 levels were significantly increased in gingivitis and chronic periodontitis patients compared with healthy individuals (p < 0.016)." (PMID 31604439, 2019). "The values of FOLR1 in GCF were higher in gingivitis and periodontitis groups than among patient in control group (p < 0.016)." (PMID 31604439, 2019). "Therefore, the present study was designed to investigate the FOLR1 levels in GCF and serum samples for healthy, gingivitis and chronic periodontitis participants." (PMID 31604439, 2019).
gynecologic cancer (2 papers, 2017 to 2024). "The folate receptor alpha (FR) has emerged as an interesting tumor target due to its overexpression in a variety of tumor types, including several gynecological cancers of epithelial origin." (PMID 28809784, 2017). "The folate receptor alpha (FR) is expressed in a variety of gynecological cancer types." (PMID 28809784, 2017).
hypomyelinating leukodystrophy (2 papers, 2014 to 2023). "Furthermore, in patients with genetically undiagnosed hypomyelination, FOLR1 should be investigated promptly and included in all leukodystrophy panels to ensure early treatment with folinic acid and optimize clinical outcomes." (PMID 37443037, 2023).
kidney cancer (2 papers, 2022 to 2024). Primary or metastatic malignant neoplasm involving the kidney. "In CCLE (Cancer Cell Line Encyclopedia), FOLR1 mRNA was barely expressed in PCa cell lines in contrast to ovarian, endometrial, and kidney cancer cells that highly expressed FOLR1 mRNA." (PMID 38396800, 2024).
Mucinous carcinomas (2 papers, 2025). "The expression level of FOLR1 is significantly higher in serous, clear cell and endometrioid carcinoma than in mucinous carcinoma." (PMID 40046734, 2025).
nasopharyngeal carcinoma (2 papers, 2019 to 2025). A carcinoma arising from the nasopharyngeal epithelium. "Conversely, reducing FOLR1 levels alters key apoptotic and MAPK pathway genes (BIRC3, caspases, FOS, DUSP1, PRKX, TNFRSF10A), sensitizing taxol-resistant nasopharyngeal carcinoma cells to chemotherapy." (PMID 41439026, 2025).
osteosarcoma (2 papers, 2019 to 2025). A usually aggressive malignant bone-forming mesenchymal neoplasm, predominantly affecting adolescents and young adults. "FOLR1 expression has previously been implicated in the pathogenesis of treatment-resistant osteosarcoma." (PMID 40919994, 2025). "Folate receptor-α (FOLR1) has been functionally implicated in osteosarcoma pathophysiology, providing rationale as a potential therapeutic target." (PMID 40919994, 2025). "The role of FOLR1 and its implications in therapy-resistant osteosarcoma has previously been described." (PMID 40919994, 2025). "Whereas a previous study describes FOLR1 overexpression in 78.5% of 107 patient-derived osteosarcoma specimens, our analysis of publicly available genomic data through St." (PMID 40919994, 2025). "FH FOLR1-CART exhibits robust in vitro activation and potent cytotoxicity against FOLR1-expressing osteosarcoma cell lines and primary osteosarcoma patient samples." (PMID 40919994, 2025). "This article provides detailed in vitro evaluation of our FOLR1-CART in a standard osteosarcoma cell line, as well as multiple patient-derived cell lines." (PMID 40919994, 2025). "Although it is known that mRNA expression does not directly correlate with protein expression, we validated FOLR1 tumor surface expression in multiple patient-derived osteosarcoma cell lines and tumors, as detected by flow cytometry." (PMID 40919994, 2025). "Jude’s PCGP, the PIVOT, and the Open Pediatric Cancer Project v15 further demonstrates that most osteosarcoma patient specimens exhibit increased FOLR1 mRNA expression." (PMID 40919994, 2025). "FOLR1 transcript is expressed in the overwhelming majority of osteosarcoma primary patient specimens, osteosarcoma cell lines, and patient-derived models." (PMID 40919994, 2025). "We provide comprehensive FOLR1 transcript and protein expression profile in patients with osteosarcoma, cell lines, and patient-derived xenografts, substantiating its significance as a therapeutic target." (PMID 40919994, 2025). "Five of seven osteosarcoma patient-derived cell lines or tissue demonstrated high FOLR1 surface expression by flow cytometry, with MFI ranging from 817 to 8,930 or 4.3- to 159.5-fold increase from isotype control." (PMID 40919994, 2025). "In our goal to broaden the use of FH FOLR1-CART to other difficult-to-treat malignancies, we provide potent in vitro and in vivo evidence of FH FOLR1-CART activity against osteosarcoma." (PMID 40919994, 2025). "Whereas samples from most other tumors demonstrated little or no FOLR1 expression (<2 FPKM), a majority of osteosarcoma tumor samples demonstrated FOLR1 expression with a median FOLR1 mRNA expression of 5.614 (n = 113; range, 0–84.12)." (PMID 40919994, 2025).
schizophrenia (2 papers, 2022 to 2023). A major psychotic disorder characterized by abnormalities in the perception or expression of reality. "In a small study, authors reported that 83% of their 18 patients with schizophrenia and only 3.3% of 30 controls (p < 0.0001) had autoantibodies to folate receptor alpha (FRα), which blocked the transfer of MTHF into the brain." (PMID 36816414, 2023).
testicular germ cell tumor (2 papers, 2024 to 2025). A germ cell tumor arising from the testis. "For the first time, we showed significantly higher FOLR1 levels in patients with TGCTs who achieved an unfavorable response and postchemotherapy-viable tumors compared with chemotherapy-naïve testicular germ cell tumors." (PMID 39996761, 2025). "Moreover, we observed a higher level of FOLR1 in postchemotherapy-viable tumors than in chemotherapy-naïve testicular germ cell tumors." (PMID 39996761, 2025). "Importantly, FOLR1 levels in postchemotherapy-viable tumors were significantly higher than in chemotherapy-naïve testicular germ cell tumors (mean ± SD, 158.6 ± 44.0 vs. 94.1 ± 56.8, p = 0.01608)." (PMID 39996761, 2025).
Arthritis (1 paper, 2015). Inflammation of a joint. "Clinical development programs employing monoclonal antibodies specific for either folate receptor alpha in certain cancers of epithelial origin, including EOC, and folate receptor beta in inflammatory disorders such as arthritis, are underway." (PMID 25971554, 2015).
benign gynecological tumors (1 paper, 2013). "Recent data indicate that the folate-receptor 1 (FOLR1) is significantly elevated in the serum of OC patients compared to healthy controls and patients with benign gynecological tumors." (PMID 23644885, 2013).
carcinoids (1 paper, 2016). "In contrast, carcinoids present predominantly with the Ft-phenotype indicating high FOLR1 and FPGS, but low TYMS gene expression levels." (PMID 27064343, 2016). "With respect to folic acid metabolism, carcinoids showed significantly higher expression than carcinomas for FOLR1 (p<0.0001), FPGS (p<0.0001) and GGT1 (p=0.0289)." (PMID 27064343, 2016).
chronic hepatitis (1 paper, 2025). An active inflammatory process affecting the liver for more than six months. "Serum FOLR1 levels correlated with tumoral FOLR1 expression in HCC patients and were significantly elevated compared with those in patients with chronic hepatitis or nonliver disease." (PMID 40038575, 2025).
cleft lip (1 paper, 2024). Congenital defect in the upper lip where the maxillary prominence fails to merge with the merged medial nasal prominences. "Indeed, dietary folinic acid supplementation rescued the early embryonic lethal phenotype of Folr1-/- mice, enabling their survival to adulthood and partially rescuing the cleft lip phenotype in Clpex mutants." (PMID 40225942, 2024).
Down syndrome (1 paper, 2025). "For example, collagen dysregulation and oxidative stress were documented in Down syndrome placentas, while FOLR1 was reported essential for folate transport and fetal neural development, linking it to altered folate metabolism in aneuploidy." (PMID 41614738, 2025).
epileptic encephalopathies (1 paper, 2025). "In another cohort of 205 patients with developmental and epileptic encephalopathies under the age of three years, only one patient was diagnosed with FOLR1 deficiency, while a smaller, similar-age cohort yielded no diagnoses." (PMID 41300631, 2025).
fallopian tube adenocarcinoma (1 paper, 2015). "In some cases, FOLR1 expression in fallopian tube adenocarcinoma appeared more highly expressed relative to normal fallopian tube, suggesting the potential of increased expression of FOLR1 mRNA." (PMID 25971554, 2015).
Insulin resistance (1 paper, 2023). Increased resistance towards insulin, that is, diminished effectiveness of insulin in reducing blood glucose levels. "In addition, several energy metabolic processes, such as the PI3K-Akt pathway (EPHA2, FLT4, ITGA5, and LPAR6), cholesterol metabolism (APOE and CD36), and insulin resistance (FOLR1, CALM14, and PPP1R3A), were enriched in ApoE4 mice." (PMID 36720919, 2023).
LAMM syndrome (1 paper, 2025). "One of the first publications on this subject in the literature reported the combination of FOLR1-related CFD and LAMM syndrome." (PMID 40218241, 2025).
metastatic cancer (1 paper, 2021). A carcinoma which has spread from the original site of growth to another anatomic site. "FOLR1 transcript was remarkably reduced in metastatic cancer cells compared to primary cells." (PMID 34055623, 2021).
myoclonic epilepsy (1 paper, 2020). A group of epilepsy syndromes in which myoclonic seizures are a prominent feature. "Although homozygous mutations and SNPs in FOLR1 were reported in the literature to cause progressive ataxia and myoclonic epilepsy and elevated levels of homocysteine, respectively, the role of heterozygous mutations or SNPs in FOLR1 on human milk production and content remains to be established." (PMID 32455695, 2020).
neuroendocrine tumor (1 paper, 2019). "Moreover, in neuroendocrine tumor, low FOLR1 expression was also identified as a marker for more aggression and associated with shorter OS and PFS." (PMID 31049278, 2019).